RTP1 (receptor transporter protein 1)
Description:
Specifically promotes functional cell surface expression of olfactory receptors, but not of other GPCRs.
Synonyms: Z3CXXC1; MGC35450
Tractability: Antibody: UniProt places it where antibodies can reach, with medium confidence; UniProt predicts a signal peptide or a membrane-spanning region; its Gene Ontology location is reachable by antibodies, with medium confidence.
Gene: Protein-coding gene on chromosome 3 (187,197,486 to 187,201,462, forward strand). Ensembl gene ENSG00000175077.
Subcellular location: Cell membrane
Pathways (Reactome):
Sensory Perception: Expression and translocation of olfactory receptors
Gene Ontology:
Molecular function: olfactory receptor binding
Biological process: protein insertion into membrane; detection of chemical stimulus involved in sensory perception of bitter taste; protein targeting to membrane
Cellular component: cell surface; plasma membrane
Genetic constraint (gnomAD): Loss-of-function variants: 24 observed, 24 expected, observed/expected ratio (o/e) 1, 90% interval 0.72 to 1.41. The upper end of that interval is the gene's LOEUF score, 1.41, which puts it in group 5 of 6, group 1 being the genes least tolerant of losing a copy. Missense variants: 338 observed, 343.42 expected, observed/expected ratio (o/e) 0.98, 90% interval 0.9 to 1.08. Synonymous variants: 148 observed, 144.08 expected, observed/expected ratio (o/e) 1.03, 90% interval 0.9 to 1.18.
Homologues: Orthologues: chimpanzee RTP1 (99% identical), macaque RTP1 (97% identical), pig RTP1 (95% identical), rabbit RTP1 (95% identical), dog RTP1 (91% identical), rat Rtp1 (90% identical), guinea pig RTP1 (88% identical), mouse Rtp1 (88% identical). Paralogues in human: RTP2 (70% identical), RTP3 (24% identical), RTP4 (23% identical), RTP5 (22% identical).
Diseases named in the same sentence as RTP1 in open-access papers:
RTP1 is named in the same sentence as 6 diseases in open-access papers, as found by Europe PMC text mining. Sharing a sentence is not in itself a finding about the gene and the disease. The quoted sentences say what the papers report.
colitis (1 paper, 2015). Inflammation of the colon. "RTP1 can also clearly reduce the mortality of rats with colitis induced by 2,4,6- trinitro-benzene-sulphonic acid, reduce colon weight, deflate colon ulcer area and alleviate mucosal oedema." (PMID 26330871, 2015). "Animal experiments showed that RTP1 (molecular weight of 6 × 105 to 8 × 105) can significantly reduce the mortality of rats with 2,4,6-trinitrobenzene sulphonic acid-induced colitis by reducing the weight of the colon, thereby narrowing the ulcer area and relieving mucosal oedema." (PMID 26330871, 2015).
epilepsy (1 paper, 2017). A brain disorder characterized by episodes of abnormally increased neuronal discharge resulting in transient episodes of sensory or motor neurological dysfunction, or psychic dysfunction. "Interestingly, co-expression and genetic interaction network analyses suggested that DYNC1H1 and RTP1 are tightly associated with known epilepsy genes." (PMID 28325891, 2017). "In addition, we detected a co-expression relationship between RTP1 and 17 genes associated with epilepsy (significance p = 0.025, Fisher’s exact test), almost half of which belong to the high-confidence genes (significance p = 0.012, Fisher’s exact test)." (PMID 28325891, 2017). "Within this genetic interaction network, 12 high-confidence genes associated with epilepsy were detected in the network analysis of DYNC1H1, in addition to 9 genes for RTP1." (PMID 28325891, 2017). "Overall, the co-expression and genetic interactions network analyses indicated that DYNC1H1 and RTP1 may share a similar role with several candidate epilepsy genes." (PMID 28325891, 2017).
gastric ulcer (1 paper, 2015). An ulcerated lesion in the mucosal surface of the stomach. "Our previous studies have shown that RTP1 has obvious protective effect on the stress gastric ulcer in rats caused by water bondage stress." (PMID 26330871, 2015).
osteosarcoma (1 paper, 2021). A usually aggressive malignant bone-forming mesenchymal neoplasm, predominantly affecting adolescents and young adults. "We found RTP1 played an important role in the PPI network, suggesting RTP1 is a potential biomarker that regulates the prognosis of osteosarcoma." (PMID 33964903, 2021). "Additionally, PPI network suggested RTP1 is a potential biomarker that regulates the prognosis of osteosarcoma." (PMID 33964903, 2021).
xerostomia (1 paper, 2022). Dryness of the mouth resulting from reduced salivary secretion. "The most prominent findings in our study included potential associations of ANTXR1, RTP1, GLT1D1, NLRP9, and EGFLAM genes with xerostomia." (PMID 35459784, 2022).
infection (2 papers, 2014 to 2017). The state of being infected such as from the introduction of a foreign agent such as serum, vaccine, antigenic substance or organism. "(2013) showed that the RTP1 protein exhibits variable localization in the extra‐haustorial matrix and in the interior of the host cell during infection." (PMID 27918080, 2017). "RTP1 also exhibits a dynamic pattern of localization in the extra-haustorial matrix and within host cells during the infection process, illustrating once more that rust effectors deployment is probably finely regulated in time and space." (PMID 25191335, 2014). "RTP1 and AvrM have been directly shown to traffic from haustoria to plant cells during infection, whereas the direct recognition of AvrM and AvrL567 by cytosolic plant immune receptors indirectly demonstrates their internalization in the plant cell." (PMID 25191335, 2014).